SPATA19 (spermatogenesis associated 19)
Description:
Essential for sperm motility and male fertility (By similarity). Plays an important role in sperm motility by regulating the organization and function of the mitochondria and is also required for correct sperm midpiece assembly (By similarity).
Synonyms: SPERGEN1; FLJ25851; SPAS1; CT132
Tractability: No criterion of Open Targets' tractability assessment is met for any kind of drug.
Gene: Protein-coding gene on chromosome 11 (133,840,631 to 133,845,538, reverse strand). Ensembl gene ENSG00000166118.
Subcellular location: Mitochondrion outer membrane; Mitochondrion; Cell projection, cilium, flagellum
Gene Ontology:
Biological process: sperm mitochondrion organization
Cellular component: mitochondrion; mitochondrial outer membrane; sperm flagellum; sperm midpiece; motile cilium
Genetic constraint (gnomAD): Loss-of-function variants: 19 observed, 26.37 expected, observed/expected ratio (o/e) 0.72, 90% interval 0.5 to 1.06. The upper end of that interval is the gene's LOEUF score, 1.06, which puts it in group 4 of 6, group 1 being the genes least tolerant of losing a copy. Missense variants: 222 observed, 222.72 expected, observed/expected ratio (o/e) 1, 90% interval 0.89 to 1.11. Synonymous variants: 64 observed, 73.21 expected, observed/expected ratio (o/e) 0.87, 90% interval 0.71 to 1.08.
Homologues: Orthologues: chimpanzee SPATA19 (99% identical), macaque SPATA19 (95% identical), rabbit SPATA19 (74% identical), dog SPATA19 (72% identical), pig SPATA19 (70% identical), mouse Spata19 (66% identical), guinea pig SPATA19 (66% identical), rat Spata19 (63% identical).
Diseases named in the same sentence as SPATA19 in open-access papers:
SPATA19 is named in the same sentence as 13 diseases in open-access papers, as found by Europe PMC text mining. Sharing a sentence is not in itself a finding about the gene and the disease. The quoted sentences say what the papers report.
prostate carcinoma (5 papers, 2012 to 2025). A carcinoma that arises from epithelial cells of the prostate gland. "Spata19 has also been identified as an antigen in benign prostatic hyperplasia and prostate cancer." (PMID 40256767, 2025). "Previously, our studies showed expression of TEX101, SPATA19 and LEMD1 in basal cell carcinoma and prostate cancer." (PMID 23396665, 2012).
male infertility (2 papers, 2018 to 2025). The inability of the male to effect fertilization of an ovum after a specified period of unprotected intercourse. "It has been reported that deficiency of the genes with similar expression profile, such as Zmym3, Ku70, Fam46d, Pdha2, Tex101 and Spata19, etc. always resulted in spermatogenic problems leading to male infertility, thus validating the essential roles of these genes." (PMID 29563520, 2018).
Down syndrome (1 paper, 2025). "Based on gene ontology studies in Fragile X and Down syndrome human neural progenitor cells, SPATA19 is involved in brain development, neurogenesis, and glial cell differentiation." (PMID 40307894, 2025).
SPATA19 also shares sentences with these, for which no sentence is quoted: tumor (5 papers); prostate tumors (2); prostatic adenocarcinoma (2); basal cell carcinoma (1); benign prostatic hyperplasia (1); breast carcinoma (1); cancer (1); ductal carcinoma (1); Fibroadenoma (1); infection (1).